CDKN2A (cyclin dependent kinase inhibitor 2A)
Diseases named in the same sentence as CDKN2A in open-access papers (continued):
Sharing a sentence is not in itself a finding about the gene and the disease.
melanoma (continued). "Moreover, MC1R mutations have a synergistic effect with other melanoma-associated mutations, particularly in CDKN2A and BRAF, further amplifying melanoma risk." (PMID 40507265, 2025). "CDKN2A, cyclin-dependent kinase inhibitor 2A, is a major gene associated with melanoma." (PMID 40290801, 2025). "Moreover, 74% of families with pancreatic cancer harbored a CDKN2A mutation compared to 33% of those families with only melanoma." (PMID 39609109, 2025). "Finally, some studies have also investigated the different survival in familial melanoma patients according to their CDKN2A mutation status." (PMID 40869905, 2025). "The clinical syndrome of a CDKN2A mutation resulting in melanomas suggests that melanocytes may be more reliant of the p16INK4a/Rb pathway than other cutaneous cell types to become senescent." (PMID 39420514, 2025). "Germline mutations in CDKN2A can cause a hereditary form of melanoma." (PMID 40687210, 2025). "The oncogenic mechanisms of the PTEN/phosphoinositol-3-kinase signaling pathway, RAC1, CDKN2A, telomerase reverse transcriptase promoter mutations, and several molecular alterations specific to mucosal and chronically sun-damaged melanomas have also been implicated in disease progression." (PMID 40075679, 2025). "In conclusion, we report an exceptional case of somatic mosaicism for a distinct 19-base-pair deletion in the CDKN2A gene, historically recognized solely as a Dutch population-specific germline founder variant in the context of hereditary melanoma and pancreatic cancer." (PMID 40917369, 2025). "However, emerging research has highlighted the importance of additional non-CDKN2A genes, many of which are also occasionally mutated in melanoma cases." (PMID 40558591, 2025). "While early stage (I-IIA) melanoma has 5-year overall survival rates of greater than 90%, it worsens in more advanced disease Melanoma arises in melanocytes due to a combination of genetic predisposition (CDKN2A, CDK4) and acquired mutations (BRAF, MEK) from ultraviolet light-induced damage." (PMID 39602056, 2024). "Mutations in CDKN2A are found in approximately 20–40% of familial melanoma cases." (PMID 39518584, 2024). "Focusing on the different trends across Italian regions, in the Veneto region, CDKN2A mutations occurred only in a small number (8,5%) of familial melanoma cases with at least two relatives affected by melanoma, suggesting the contribution of other genetic factors to melanoma susceptibility." (PMID 39596909, 2024). "Patients with CDKN2A mutation are at a high risk of developing melanomas and PC." (PMID 38303549, 2024). "For example, families with melanoma who have germline mutations in CDKN2A are well known, whereas the vast majority of sporadic melanomas have mutations in the mitogen-activated protein kinase (MAPK) cascade, which is the pathway with the highest oncogenic and therapeutic relevance for this disease." (PMID 38672402, 2024). "Moreover, given the fact that the patient is a carrier of the CDKN2A mutation, she was counseled regarding the risk of familial melanoma and regular cutaneous examinations were recommended for her two daughters." (PMID 38792946, 2024). "Loss of CDKN2A may result in the accumulation of more mutations in melanomas, leading to the production of additional neoantigens and subsequently enhancing immune responses." (PMID 38534309, 2024). "Mutations in CDKN2A are also detected in sporadic melanoma patients." (PMID 38473375, 2024). "However, there exists a paucity of animal models for the rare hereditary melanoma resulting from germline CDKN2A mutations." (PMID 39659584, 2024). "Furthermore, individuals with hereditary melanoma caused by germline CDKN2A mutations exhibit a more effective response to immunotherapy." (PMID 38534309, 2024).
melanoma (continued). "A study of the world’s largest melanoma database showed a significant association between pancreatic cancer and CDKN2A mutation in melanoma multiplex families, with 28% of mutation-positive kindreds having pancreatic cancer as compared to 6% in patients without the mutation." (PMID 39200847, 2024). "Mutations in cyclin dependent kinase inhibitor 2A are the most common cause of hereditary melanoma." (PMID 39188332, 2024). "Major risk factors for melanoma include high nevi count, fairer skin, cumulative or high intermittent exposure to ultraviolet radiation, gene mutations of cyclin-dependent kinase inhibitor 2A (CDKN2A) and a personal or familial history of MM." (PMID 38611119, 2024). "When observing CNAs across melanoma types, CDKN2A loss was frequent in all three." (PMID 39564955, 2024). "The ribociclib and binimetinib combination has demonstrated effectiveness in NRAS‐mutated melanoma, especially in patients with additional cell cycle gene mutations (CDKN2A, CDK4, and CCND1), who may derive greater benefit from this therapy." (PMID 39564955, 2024). "CDKN2A, located on chromosome 9p21, is the major known high-risk melanoma susceptibility gene." (PMID 38473375, 2024). "Both germline and somatic variants in CDKN2A are known to predispose for melanoma." (PMID 36883553, 2023). "CDKN2A is a well-established melanoma and pancreatic cancer predisposition gene." (PMID 37762649, 2023). "Targeting the PI3K/AKT and HIF-1α pathways may be effective for treating melanoma patients with CDKN2A mutations." (PMID 36901857, 2023). "CDKN2A mutations are responsible for the majority cases of hereditary melanoma." (PMID 36805510, 2023). "Furthermore, the epistatic effect of MC1R on CDKN2A accounts for the markedly increased risk of melanoma development in individuals carrying both genetic alterations." (PMID 37239385, 2023). "According to specific research, CDKN2A changes in melanoma patients with CDKN2A loss may serve as a possible signal for anticipating the effectiveness of melanoma immunotherapy." (PMID 38023234, 2023). "Germline alterations in CDKN2A are most frequently associated with predisposition to melanoma and pancreatic cancer but some studies describe a susceptibility to neural system tumors, breast cancer, multiple myeloma, head and neck squamous cell carcinoma and sarcoma." (PMID 36805510, 2023). "Moreover, mutations in cyclin-dependent kinase inhibitor 2A (CDKN2A) are common among human cancers including melanoma." (PMID 36768737, 2023). "The importance of the topic also resides in the oncological syndrome present in CDKN2A mutation carriers, that link melanoma and pancreatic cancer; thus, a CDKN2A-positive individual that has already developed melanoma has a 38-fold increased risk of associating pancreatic malignancies." (PMID 38134090, 2023). "In addition, a recent study identified cladribine as a possible repurposable drug in CDKN2A mutated melanoma using data mining followed by in vitro validation." (PMID 37495601, 2023). "UV radiation has also been shown to modify melanoma risk in families with CDKN2A mutations." (PMID 37504268, 2023). "These accumulating mutations include TERT (telomerase reverse transcriptase) promoter mutations, components of the SWI/SNF (switch/sucrose non-fermentable or BAF) chromatin remodeling complex and loss of CDKN2A which are early events noted along the trajectory of nevus to melanoma transition." (PMID 36834954, 2023). "CDKN2A is often deleted, mutated, or silenced by methylation in most melanomas." (PMID 37174106, 2023). "Moreover, Mutation and deletion of CDKN2A are major genetic changes discovered in melanoma cell lines." (PMID 36961395, 2023).
melanoma (continued). "Therefore, it is still challenging to correlate CDKN2A mutations and a specific pattern of melanoma evolution." (PMID 36834954, 2023). "Besides CDKN2A, other genes potentially associated with familial melanoma have also been investigated in Brazilian melanoma-prone families, such as CDK4, MITF, and TERT promoter variants." (PMID 37958811, 2023). "Such mutations may occur as a result of exposure to UV mutagenesis, while certain inherited variants of genes, such as CDKN2A, can also predispose individuals to melanoma." (PMID 37043573, 2023). "Furthermore, mutations or deletions in the CDKN2A/B gene are associated with various tumors, including breast cancer, melanoma, ovarian cancer, and lung adenocarcinoma." (PMID 37314514, 2023). "Significant players in melanoma cell cycle regulation include the CDKN2A (cyclin dependent kinase inhibitor 2A) gene which encodes the tumor suppressor p16INK4A, p14ARF, CDKs controlling specific check points of the cell cycle, and the tumor suppressor retinoblastoma protein (RB)." (PMID 37239381, 2023). "Melanoma represents an aggressive malignant tumor, encapsulating frequent loss of differentiation markers, with familial melanoma constituting a relatively commonly encountered entity, in direct relationship with cyclin-dependent kinase inhibitor 2A (CDKN2A)." (PMID 38134090, 2023). "Increased genetic risk for melanoma can occur in the context of germline pathogenic variants in high-penetrance genes, such as CDKN2A and CDK4, risk variants in low- to moderate-penetrance genes (MC1R and MITF), and possibly due to variants in emerging genes, such as ACD, TERF2IP, and TERT." (PMID 37958811, 2023). "CDKN2A mutations contribute to a lifetime risk of melanoma ranging from 28% to 67%." (PMID 38137564, 2023). "Furthermore, specific variants of MC1R are believed to increase the penetrance of CDKN2A mutations, doubling the risk of melanoma compared to a CDKN2A mutation alone." (PMID 37762707, 2023). "However, although CDKN2A mutations exist in up to 40% of high-density families, mutations in other inheritable genes have been found in less than 1% of familial melanomas." (PMID 36901857, 2023). "In melanoma cells, the function of p16 (encoded by CDKN2A) or the p16 pathway is often disrupted." (PMID 35563820, 2022). "Our results also point to an interaction between Xmrk and a genomic block containing cdkn2a/b in swordtail fish, which might cause unfit phenotypes other than melanoma." (PMID 35344560, 2022). "Importantly, we were also able to extend our analysis of germline alleles in melanoma patients to identify candidate functional variants at loci including MTAP/CDKN2A, where risk alleles were associated with phenotypes such as naevus count, and CASP8." (PMID 35357426, 2022). "In pancreatic cancer and melanoma, CDKN2A is often noticed due to mutations." (PMID 35311137, 2022). "It is also unknown how individuals with a CDKN2A PV may make behavioral changes regarding their pancreatic cancer risk, given there is greater individual control over melanoma prevention than pancreatic cancer prevention, at least at this time." (PMID 35372037, 2022). "CDKN2A locus encodes p16INK4A and is found mutated in 25% of melanoma types." (PMID 36135270, 2022). "In addition to the increased risk of melanoma, pancreatic cancer, and neural systems tumor, various cancers have been reported in patients with germline CDKN2A mutation." (PMID 35123577, 2022). "Other factors include high risk of CDKN2A mutations and a positive family history of melanoma." (PMID 35566480, 2022).
melanoma (continued). "Data regarding the prevalence of CDKN2A germline mutations in Brazilian patients fulfilling clinical criteria for familial melanoma are scarce; differ by geographic region and adopted diagnostic criteria; and disclose prevalence rates that vary from 4.5% to 14%." (PMID 35085295, 2022). "CDKN2A was first associated with familial melanoma predisposition." (PMID 36614156, 2022). "CDKN2A germline mutations are associated with a 65-fold increase in the risk of melanoma development, and these have been identified in approximately 20–40% of families showing a predisposition to melanoma." (PMID 35320498, 2022). "Additionally, codeletion of CDKN2A and the interferon α and β cluster has been linked with decreased expression of immune cell genes in melanoma tumors." (PMID 33918220, 2021). "Furthermore, germline carriers of the CDKN2A p16-Leiden deletion mutation in a large collection of Dutch families showed an increased risk of melanoma in carriers of MC1R variant alleles, with the R151C allele explaining most of this association." (PMID 34356109, 2021). "We compared drug sensitivity to CDKN2A mutations identified in melanoma cell lines." (PMID 33627666, 2021). "While the loss of the CDKN2A/B locus is a formative event in melanoma progression, genetic evolution studies of melanoma progression suggest that selection against the CDKN2A/B locus occurs after BRAFV600E melanocytes have already escaped nevus-associated arrest." (PMID 34812139, 2021). "However, germline CDKN2A variants are rare, and only a subset of CDKN2A positive patients with primary melanoma ultimately develop distant metastases and need systemic therapy." (PMID 34069952, 2021). "Although CDKN2A is well-known as a susceptibility gene for melanoma and pancreatic cancer, germline variants have also been anecdotally associated with a broader range of neoplasms including neural system tumors, head and neck squamous cell carcinomas, breast carcinomas, as well as sarcomas." (PMID 33766116, 2021). "Moreover, germline CDKN2A mutations have been shown to increase the susceptibility to develop melanomas." (PMID 34071228, 2021). "One sporadic melanoma MITF-E318K carrier resulted wild-type for CDKN2A and MC1R genes and displayed only germline variants of unknown significance in ATM and Fanconi anemia complementation group I (FANCI) genes." (PMID 34573422, 2021). "Moreover, it has been reported in scientific literature that germline variants, such as MC1R, CDKN2A, and p16 gene variants are also associated with increased risk of melanoma." (PMID 34195089, 2021). "Bi-allelic loss of CDKN2A is correlated with aggressive initiation of melanoma." (PMID 34804979, 2021). "However, CDKN2A-mutation carriers in melanoma-prone families have a higher risk of melanoma than CDKN2A-mutation carriers in the general population, increasing the risk of melanoma by up to 75-fold." (PMID 34356093, 2021). "Furthermore, MC1R variants double the risk of melanoma in CDKN2A mutation carriers, which is three times higher in carriers of the RHC variants." (PMID 34442055, 2021). "Inherited cases of malignant melanoma have been largely associated with mutation to a number of high penetrance genes, although mutation to the cyclin-dependent kinase inhibitor 2A (CDKN2A) gene located on chromosome 9 is documented as the most penetrant mutation to cause melanoma." (PMID 34155457, 2021).
melanoma (continued). "Among the tumour suppressor genes with frequent promoter hypermethylation in melanomas, causing repression of transcription, are CDKN2A, Ras association domain family member 1 (RASSF1A), and PTEN, with the latter two particularly becoming hypermethylated in later stages of the disease." (PMID 34680938, 2021). "To schematize, going from nevus to melanoma is necessary the loss of cyclin dependent kinase inhibitor 2A (CDKN2A) and phosphatase and tensin homologue (PTEN), together with the down-regulation of MITF master gene in the evolution from radial to vertical growth phase melanoma." (PMID 34207514, 2021). "Familial melanoma and CDKN2A mutation could be associated with different type of cancers, especially pancreas." (PMID 34711012, 2021). "Some clinical features found in germline CDKN2A mutation carriers include a minor age at melanoma diagnosis, the presence of multiple primary melanomas, a tendency to develop superficial spreading melanomas in the absence of severe sunburns and a very low proportion of acral and nodular melanomas." (PMID 34442055, 2021). "In this familial context, CDKN2A germline mutations increase the risk of developing melanoma up to 75-fold under the influence of shared risk factors such as UV exposure, sunburn, and atypical moles, but not the total number of common nevi or phenotypic traits." (PMID 34356093, 2021). "Familial melanomas account for about 10% of all malignant melanomas and display an inheritance pattern consistent with the presence of pathogenic germline mutations, among which those involving CDKN2A are the best characterized." (PMID 34442055, 2021). "Our aim was to use this approach to explore differential gene expression profiles in healthy skin keratinocyte-melanocyte co-cultures from familial melanoma patients, including both CDKN2A mutated and CDKN2A wild-type affected members, to identify novel pathways involved in melanoma susceptibility." (PMID 34660619, 2021). "Germline CDKN2A mutations ocuur in 5-20% familial melanoma cases." (PMID 34711012, 2021). "Although the onset of melanoma at a young age is quite common in subjects carrying CDKN2A mutations, it cannot be considered a predictor of the presence of the mutation; less than 1% of individuals diagnosed with melanoma before the age of 40 age are, in fact, positive for this mutation." (PMID 34442055, 2021). "Variants in CDKN2A and other intronic mutations have also been described to predispose to melanoma." (PMID 34123788, 2021). "Nevertheless, the fact that melanoma penetrance in CDKN2A mutation carriers is also higher in high-incidence areas indicates that there may be potential interactions between genetic factors and other predisposing factors in the carriers." (PMID 34442055, 2021). "In addition to melanomas, there exist many other tumors and syndromes associated with CDKN2A mutations, with pancreatic cancer being the most widely documented." (PMID 34442055, 2021). "Germline mutations in CDKN2A affecting the encoded p16INK4A protein (hereafter referred to as p16) are a major risk factor for familial melanoma, with a high proportion (40–60%) of families in which multiple individuals develop melanoma-carrying germline mutations in CDKN2A." (PMID 33823155, 2021). "Familial melanoma accounts for 10% of cases, being CDKN2A the main high-risk gene." (PMID 34660619, 2021). "CDKN2A mutations are most common in patients with heredity melanoma." (PMID 34203771, 2021).